MYCL (MYCL proto-oncogene, bHLH transcription factor)
Synonyms: bHLHe38; LMYC; MYCL1; L-Myc
Tractability: No criterion of Open Targets' tractability assessment is met for any kind of drug.
Gene: Protein-coding gene on chromosome 1 (39,895,428 to 39,902,256, reverse strand). Ensembl gene ENSG00000116990.
Subcellular location: Nucleus
Subcellular location (Human Protein Atlas): Nucleoplasm; Mitotic chromosome
Gene Ontology:
Molecular function: DNA binding; DNA-binding transcription factor activity, RNA polymerase II-specific; RNA polymerase II cis-regulatory region sequence-specific DNA binding; DNA-binding transcription factor activity; protein dimerization activity
Biological process: regulation of transcription by RNA polymerase II; regulation of DNA-templated transcription
Cellular component: chromosome; nucleoplasm; chromatin; nucleus
Genetic constraint (gnomAD): Loss-of-function variants: 11 observed, 29.53 expected, observed/expected ratio (o/e) 0.37, 90% interval 0.23 to 0.62. The upper end of that interval is the gene's LOEUF score, 0.62, which puts it in group 2 of 6, group 1 being the genes least tolerant of losing a copy. Missense variants: 426 observed, 476.3 expected, observed/expected ratio (o/e) 0.89, 90% interval 0.82 to 0.97. Synonymous variants: 208 observed, 197.07 expected, observed/expected ratio (o/e) 1.06, 90% interval 0.94 to 1.18.
Homologues: Orthologues: chimpanzee MYCL (99% identical), macaque MYCL (99% identical), dog MYCL (93% identical), guinea pig MYCL (93% identical), rabbit MYCL (91% identical), mouse Mycl (90% identical), rat Mycl (90% identical), zebrafish myclb (51% identical), tropical clawed frog mycl (48% identical), zebrafish mycla (42% identical). Paralogues in human: MYCN (40% identical), MYC (35% identical).
Diseases named in the same sentence as MYCL in open-access papers:
MYCL is named in the same sentence as 72 diseases in open-access papers, as found by Europe PMC text mining. Sharing a sentence is not in itself a finding about the gene and the disease. The quoted sentences say what the papers report.
lung carcinoma (25 papers, 1990 to 2024). "The FAXDC2 gene induces megakaryocyte differentiation whereas MYCL encodes a transcription factor concerned in lung cancer." (PMID 34125870, 2021). "Its two paralogs, N-Myc and L-Myc, which are encoded by MYCN and MYCL genes, were respectively identified in neuroblastoma and lung cancer as more tissue-specific factors." (PMID 30597997, 2018). "Myelocytomatosis oncogene (MYC) family members, including cellular MYC (c-Myc), neuroblastoma derived MYC (MYCN), and lung carcinoma derived MYC (MYCL), have all been implicated as key oncogenic drivers in a broad range of human cancers." (PMID 28245597, 2017). "MYCL is a proto-oncogene associated with the apocrine adenosis of breast and lung cancer." (PMID 37375208, 2023). "Two additional human paralogs were eventually identified: MYCN (N-Myc) and MYCL (L-Myc) that can be found in neuroblastoma and lung cancer samples, respectively." (PMID 35267559, 2022). "Two additional human paralogs were eventually identified: MYCN (N-Myc) initially observed in neuroblastoma, and MYCL (L-Myc) identified in lung cancer samples." (PMID 32331235, 2020). "As a member of the myelocytomatosis oncogene family, MYCL is a driver oncogene of lung carcinoma." (PMID 29697361, 2018). "Laura Soucek and his colleagues suggested that MYC, MYCL and MYCN might be therapeutic targets for lung cancer and that elevated Myc levels were also associated with treatment resistance, there may be significant opportunities for the combination of Myc inhibitors with immunotherapies." (PMID 36299592, 2022).
small cell lung carcinoma (25 papers, 2010 to 2025). Small cell lung cancer (SCLC) is a highly aggressive malignant neoplasm, accounting for 10-15% of lung cancer cases, characterized byrapid growth, and early metastasis. "MYCN is most frequently overexpressed in cancers of neural origin and also regulates genes functioning in ribogenesis, whereas MYCL is most often overexpressed in small cell lung carcinomas." (PMID 38225354, 2024). "MYCL appears frequently overexpressed in small cell lung cancer, but it is still the least explored member of the MYC family." (PMID 33635497, 2021). "For instance, MYC genes (MYC, MYCN and MYCL) are amplified and/or overexpressed in 15–30% of small cell lung cancer (SCLC) but less frequently in NSCLC." (PMID 28152508, 2017). "For example, amplification of MYCL or the presence of the RLF-MYCL1 fusion gene are mutually exclusive of amplifications of MYC or MYCN in small cell lung cancer." (PMID 29028833, 2017). "We aimed to elucidate the effect of JQ1, a BET inhibitor, on small cell lung cancers (SCLCs) with MYCL amplification and/or expression." (PMID 27764802, 2016). "MYCL amplifications and gene fusions have also been identified and shown to drive proliferation in small cell lung carcinomas." (PMID 26444865, 2015). "In addition, studies of multiple small cell lung cancer (SCLC) cell lines found that the MYCL gene on ecDNA can significantly increase MYCL expression by hijacking the RLF promoter." (PMID 41030947, 2025). "Soon after, amplifications of MYCN and MYCL were discovered in cell lines and tumors of neuroblastoma and small cell lung cancer, respectively, with small cell lung cancer being the first cancer found to have amplifications of all three transforming MYC family members." (PMID 28587062, 2017). "Intriguingly, one study found that a significant number of MCC tumors contained genomic amplification of MYCL, a close relative of MYC that is also amplified in small cell lung cancer." (PMID 27880818, 2016). "Notably, other HLA-I–low neuroendocrine cancers such as small cell lung cancer and neuroblastoma featured overexpression of the MYC family proteins MYCL and MYCN, respectively." (PMID 35775490, 2022). "The lack of HIF-1α may be compensated by MYC/MYCL-mediated glutaminolysis, which circumvents HIF-1α-dependent glycolysis in human small cell lung carcinoma cell lines during hypoxia." (PMID 31036602, 2019).
neuroblastoma (15 papers, 2013 to 2024). Neuroblastoma (NB) is the most common solid, extracranial childhood tumor. "As MYCL is located on chromosome 1p, a frequently deleted region in neuroblastoma, MYCL loss appears to be frequent in neuroblastoma lines." (PMID 37255415, 2023). "As members of the Myc oncogene family (MYC, MYCN, and MYCL) have been implicated in SCLC and neuroblastoma oncogenesis, we attempted to dissect their relationship with the NE state." (PMID 37255415, 2023). "Subsequently, two MYC paralogues, MYCN (initially identified in neuroblastomas) and MYCL, were cloned in neuroblastoma and lung cancers, respectively." (PMID 34201047, 2021). "We found that MYC and MYCL were enriched in high-NE-score SCLC lines, whereas MYCN amplification was enriched in high-NE-score neuroblastoma lines." (PMID 37255415, 2023). "Subsequently, other transcriptionally addicted malignancies, including MYCN-amplified neuroblastoma and MYC/MYCL-amplified SCLC showed also sensitivity to CDK7 inhibition." (PMID 33686962, 2021).
medulloblastoma (5 papers, 2012 to 2024). A malignant, invasive embryonal neoplasm arising from the cerebellum. "For the MYCL gene we obtained the highest expression in the medulloblastomas (ddCt = 2.15), followed by pilocytic astrocytomas." (PMID 33430425, 2021). "High-level gene amplifications are overall rarely observed in medulloblastoma, but when they do occur, they most frequently affect the MYC or MYCN oncogenes and only in a very few cases the related MYCL gene." (PMID 22358457, 2012). "Among those tumors, medulloblastoma is grouped into four distinct molecular subgroups in terms of gene expression patterns, one of which is SHH group, in which the amplifications of MYCN and MYCL are most frequently observed, defining its pathological significance in medulloblastoma." (PMID 38884091, 2024).
ovarian carcinoma (5 papers, 2008 to 2023). A malignant neoplasm originating from the surface ovarian epithelium. "c-MYC copy-number amplifications have been reported in up to 50% of ovarian carcinomas, whereas MYCL copy-number amplifications and gene overexpression have been reported in upwards of 21% of ovarian carcinomas." (PMID 36765581, 2023). "c-MYC and its paralogues MYCN and MYCL are among the most frequently amplified and/or overexpressed oncoproteins in ovarian cancer." (PMID 36765581, 2023). "MYCL and MYCN gene transcripts also are overexpressed in some ovarian cancers." (PMID 36765581, 2023).
prostate carcinoma (5 papers, 2016 to 2026). A carcinoma that arises from epithelial cells of the prostate gland. "Although MYC family oncogenes are central to prostate cancer progression, the role of MYCL (L-MYC) in NEPC has remained poorly defined." (PMID 42001796, 2026). "In contrast, CAV2 induces various epithelium-related molecules, including Vimentin, N-Cadherin, E-Cadherin, MMP13, and MYCL, which play important roles in prostate cancer cell motility." (PMID 35517414, 2022). "c-Myc, a well-known oncogene, has been reported to cooperate with family members MYCN and MYCL to promote the tumorigenesis of prostatic cancer." (PMID 34657603, 2021). "Also identified is MYCL as a novel driver of prostate cancer NE phenotype which too was expressed in ACRJ-PC28 at RNA and protein levels." (PMID 36643868, 2022). "Together, these findings identify MYCL as a lineage-specific regulator that drives and maintains neuroendocrine identity and define a MYC family regulatory switch in which MYCL replaces MYC to stabilize neuroendocrine lineage programs in advanced prostate cancer." (PMID 42001796, 2026).
gastric cancer (4 papers, 1990 to 2021). A primary or metastatic malignant neoplasm involving the stomach. "Other than SCLC, amplification and/or expression of MYCL have been detected only in ovarian and gastric cancer, although its biological significance is still unknown." (PMID 27764802, 2016).
leukemia (3 papers, 1989 to 2022). A malignant (clonal) hematologic disorder, involving hematopoietic stem cells and characterized by the presence of primitive or atypical myeloid or lymphoid cells in the bone marrow and the blood. "However, MLN8237 showed no influence on the expression of MYC and MYCL in leukemia cell lines." (PMID 29022893, 2017).
carcinoids (2 papers, 2017). "There were fewer CNAs in carcinoids than in carcinomas; however ACs showed a hybrid pattern, whereby gains of TERT, SDHA, RICTOR, PIK3CA, MYCL and SRC were found at rates similar to those in carcinomas, whereas the MEN1 loss rate mirrored that of TCs." (PMID 27873319, 2017).
diabetes (2 papers, 2024 to 2025). "Sex differences in HCL and MYCL may be associated with a higher cardiovascular disease risk observed in female individuals progressing to diabetes." (PMID 39558211, 2024). "Increased MYCL was reported in individuals with insulin resistance, OB, and diabetes, as well as in those with increasing age, and is a relevant determinant of cardiac function." (PMID 39558211, 2024).
Hyperglycemia (2 papers, 2024 to 2025). An increased concentration of glucose in the blood. "This is in line with an earlier study, which also reported a stronger increase of MYCL in female individuals with hyperglycemia (impaired glucose tolerance [IGT] or T2DM combined)." (PMID 39558211, 2024). "No sex differences in MYCL at baseline were observed, and similar increases in male and female healthy participants with normal weight were demonstrated in a small experimental study during a hyperglycemic‐hyperinsulinemic clamp inducing short‐term hyperglycemia." (PMID 39558211, 2024).
lung adenocarcinoma (2 papers, 2017 to 2018). A carcinoma that arises from the lung and is characterized by the presence of malignant glandular epithelial cells. "In another study that comparatively analyzed 660 lung adenocarcinomas and 484 SCC cases MYC amplification was observed in both adenocarcinoma and SCC tumors, with MYCL significantly more amplified in lung adenocarcinoma." (PMID 28587062, 2017).
Merkel cell carcinoma (2 papers, 2021 to 2025). "In this study, we examined how PRMT5 regulates the Tip60-EP400 complex, which is recruited by MYCL in Merkel cell carcinoma." (PMID 40846633, 2025). "Virus-positive Merkel cell carcinoma (MCC) serves as an ideal model to explore PRMT5’s role in alternative splicing regulation, as it is driven by the MYC paralog MYCL." (PMID 40846633, 2025).
breast disease (1 paper, 2023). "MYCL (Proto-Oncogene) plays a role in breast disease and other female related cancers." (PMID 37493860, 2023).
erythroleukemia (1 paper, 2017). Acute erythroid leukemia characterised by the presence of at least 50% erythroid precursors and at least 20% myeloblasts in the bone marrow. "MYCL expression was significantly lower in the patients with erythroleukemia compared with the normal controls (P=0.011)." (PMID 29022893, 2017).
prostate tumours (1 paper, 2021). "We focused on TCGA Pan-Cancer Atlas 2018 dataset, which includes RNA-Seq data for 492 PC patients with localised disease, observing that MYCL is expressed in primary prostate tumours." (PMID 33635497, 2021).
sarcomatoid carcinoma (1 paper, 2021). A malignant epithelial neoplasm characterized by the presence of spindle cells and anaplastic morphologic features.
triple-negative breast carcinoma (1 paper, 2024). An invasive breast carcinoma which is negative for expression of estrogen receptor (ER), progesterone receptor (PR), and human epidermal growth factor receptor 2 (HER2). "The proto-oncogene MYCL promotes progression of triple negative breast cancers through activation of JAK/STAT3 pathway." (PMID 39545637, 2024).
uterine cancer (1 paper, 2021). Primary or metastatic malignant neoplasm involving the uterine corpus and/or the cervix. "For Uterine cancer, FAXDC2 and MYCL gene’s expression changed due to MTUS1 mutation." (PMID 34125870, 2021).
Wilms tumor (1 paper, 2022). An embryonal neoplasm characterized by the presence of epithelial, mesenchymal, and blastema components. "Additionally, in the Wilms tumor PDX HT139 oncoplot, there is a “start-loss” variant for MYCL where the normal “A” of start codon “AUG” is switched with a “G” so the proper translation is not initiated." (PMID 36612255, 2022). "Thus, this predicts that no MYCL protein is generated in this Wilms tumor PDX due to translational cessation." (PMID 36612255, 2022).
cancer (79 papers, 1996 to 2026). A tumor composed of atypical neoplastic, often pleomorphic cells that invade other tissues. "Deregulation of the MYC family of transcription factors c-MYC (encoded by MYC), MYCN, and MYCL is prevalent in most human cancers, with an impact on tumor initiation and progression, as well as response to therapy." (PMID 37760568, 2023). "All three tested groups were characterized by downregulation of MMP13, a protein involved in the ECM breakdown, and upregulation of MYCL, which is associated with cancer susceptibility as well as metastasis, prognosis, and adverse survival." (PMID 34579743, 2021). "The deregulation of the MYC family of oncogenes, including c-MYC, MYCN and MYCL occurs in many types of cancers, and is frequently associated with a poor prognosis." (PMID 33628735, 2020). "The Myc proto-oncogene family (MYC, MYCN, and MYCL) encodes three closely related transcription regulatory proteins that have been widely studied as critical mediators of a variety of cell functions, including dysregulated cell proliferation, metabolism, and survival in cancer." (PMID 38730731, 2024). "The c-MYC oncogenes family (MYC, MYCN, MYCL) plays a pivotal role in tumorigenesis, particularly in cancers characterized by MYC overexpression or amplification." (PMID 40710353, 2025). "The aberrant activity of the MYC family of transcription factors, which include c-MYC, MYCN, and MYCL, is frequently observed in cancer." (PMID 37760568, 2023). "PAFAH1B2 enhances aggressiveness and MYCL regulates hallmarks of cancer including proliferation and immune evasion." (PMID 37897503, 2023). "The Myc families of transcription factors (TFs), consisting of MYC, MYCN, and MYCL, are together the most commonly altered oncogenes in cancer." (PMID 36016998, 2022). "MYCL is an oncogene deregulated in human cancers, which supports tumorigenic progression and processes." (PMID 35646092, 2022). "MYC family oncoproteins MYC, MYCN, and MYCL are deregulated in diverse cancers and via diverse mechanisms." (PMID 33425720, 2020). "Aberrant up-regulation of any MYC family member (MYC, MYCN, or MYCL) promotes metabolic reprograming that leads to sustained proliferation of cancer cells." (PMID 31416966, 2019). "A relatively high frequency of overexpression of MYC was observed in kidney (48%) and colorectal (37%) cancers; of MYCL (variants 1 and 2) in uterine (58%) and breast (40%) cancers; and of MYCN in uterine (58%), liver (44%), and ovarian (43%) cancers." (PMID 28377632, 2017). "Among the nine selected cancer associated genes with germline variants SMARCB1 was downregulated and so was CNTN6, whereas MYCL was upregulated." (PMID 26998479, 2015). "Importantly, recent studies have shown that MYCN and MYCL are also expressed in other cancers, driving tumor development." (PMID 40732268, 2025). "Three myc family genes, MYC, MYCN, and MYCL, are found in ecDNA in various cancers." (PMID 37217468, 2023). "CDK7 might also be an attractive target in MYC‐driven tumors: indeed, the covalent CDK7 inhibitor THZ1 disproportionally repressed super‐enhancer regulated genes, including MYC, MYCN and MYCL in diverse cancer‐derived cell lines." (PMID 36214609, 2022). "To determine whether MYCL is related to HLA-I expression in other cancers, we queried publicly available RNA-Seq data from the Cancer Cell Line Encyclopedia." (PMID 35775490, 2022). "On the contrary, MYCL could be switching to a mesenchymal genetic program that can drive lineage plasticity and phenotypic heterogeneity, characteristic of some cancer types." (PMID 33635497, 2021). "The carcinomas had more than five times more CNVs than other devil cancers, and each harboured high copy number amplicons carrying known cancer genes (PIK3CA and MYCL, respectively), confirming that CNV mutation burden and cancer gene involvement vary across devil cancer histotypes." (PMID 33232318, 2020). "The MYC family oncogenes (MYC, MYCN, and MYCL) contribute to the genesis of many human cancers." (PMID 31452837, 2019).